RBBP5 (RB binding protein 5, histone lysine methyltransferase complex subunit)
Diseases named in the same sentence as RBBP5 in open-access papers:
RBBP5 is named in the same sentence as 29 diseases in open-access papers, as found by Europe PMC text mining. Sharing a sentence is not in itself a finding about the gene and the disease. The quoted sentences say what the papers report.
prostate carcinoma (7 papers, 2016 to 2023). A carcinoma that arises from epithelial cells of the prostate gland. "Studies have shown that RBBP5 is associated with many cancers, such as prostate cancer, hepatocellular carcinoma, and gliomas." (PMID 36866240, 2023). "In addition, previous studies have shown that RBBP5 is associated with prostate carcinoma, hepatocellular carcinoma, multiple myeloma, gliomas, etc." (PMID 36866240, 2023). "Previous studies show that in prostate cancers, TGF-β promotes H3K4me3 and Retinoblastoma binding protein 5 (RbBP5) recruitment to the Snail promoter by association with Smad2/3 and CBP, leading to enhanced Snail expression in the cancer cells." (PMID 34901003, 2021). "Here, in this study, we show that TGF-Beta1-induced EMT in the prostate cancer cell line DU145, and H3K4me3 enrichment and the binding of COMPASS complex components -WDR5/RbBP5 are increased in the vicinity of Snail transcription start site." (PMID 27566588, 2016). "Additionally, TGF-β promotes H3K4me3 and Retinoblastoma-Binding Protein 5 (RbBP5) binding to the promoter of Snail by recruiting Smad2/3 and CBP, leading to enhanced Snail expression in prostate cancer cells." (PMID 33803458, 2021). "Our study indicates that RbBP5 and even WRAD may be promising therapeutic candidates for prostate cancer metastasis treatment." (PMID 27566588, 2016). "Moreover, the recruitment of RbBP5 component of COMPASS-like complexes and the formation of H3K4me3 at SNAIL transcription start site during epithelial-mesenchymal transition are dependent on SMAD3 and CBP in the DU145 prostate cancer cell line." (PMID 34202528, 2021). "Furthermore, our results indicate that RbBP5 and even WRAD may be promising therapeutic candidates for prostate cancer metastasis treatment." (PMID 27566588, 2016). "Furthermore, our research also demonstrates that RbBP5 and even WRAD may be a promising therapeutic candidates in treating prostate cancer metastasis, and that DU145 cells maintain their incomplete mesenchymal state in an auto/paracrine manner." (PMID 27566588, 2016).
glioblastoma (5 papers, 2014 to 2025). The most malignant astrocytic tumor (WHO grade IV). "Furthermore, RBBP5 has been implicated as a potential oncogene in glioblastoma." (PMID 25187168, 2014). "Studies have shown that an increase in RBBP5 in cancer stem cells can inhibit the growth of glioblastoma." (PMID 36835467, 2023). "In glioblastoma, CSCs exhibit low TLR4 expression, which enhances retinoblastoma-binding protein 5 (RBBP5) function as a core activator of stemness transcription factors, thereby promoting CSC self-renewal and reinforcing CSC properties." (PMID 41488647, 2025).
breast carcinoma (4 papers, 2019 to 2023). "The results showed that in breast cancer patients, overexpression of RBBP5, TPR, and BCL9 was significantly associated with poor clinical outcomes (p<0.05)." (PMID 36835467, 2023). "However, our results show that the low expression of RBBP5 and BCL9 is related to a better prognosis of breast cancer, which indicates that the abnormal Wnt pathway may also be inhibited by reducing the expression of RBBP5 and BCL9 in breast cancer, thus achieving better targeted therapy." (PMID 36835467, 2023). "Other genes associating with this component were CHD3 in bladder cancer, HERC2 in ovary cancer, PIK3C2B in lung squamous cell cancer, EP300 in skin cancer (and breast cancer at a FDR of 2%), RBBP5 in pan-cancer, and SMC1B in pan-cancer." (PMID 35764656, 2022). "Among them, BCL9 was proven to be closely related to DCs in breast cancer, while the TPR and RBBP5 were shown to be closely related to DCs, but there is a lack of further research on breast cancer." (PMID 36835467, 2023).
hepatocellular carcinoma (4 papers, 2018 to 2025). A malignant tumor that arises from hepatocytes. "RBBP5, retinoblastoma binding protein 5, has been proven to be related to the progress of hepatocellular carcinoma." (PMID 39980564, 2025).
glioma (3 papers, 2018 to 2023). A benign or malignant brain and spinal cord tumor that arises from glial cells (astrocytes, oligodendrocytes, ependymal cells). "Investigation of its subunits WDR82, ASH2L DPY30 CXXC1, RBBP5, and WDR5 showed that WDR82 and WDR5 were significantly associated with WHO-grade malignancy in pediatric gliomas." (PMID 37444539, 2023). "Previous studies have shown that RBBP5 is upregulated in some types of human cancers including glioma and multiple myeloma." (PMID 30533424, 2018). "In glioma, RBBP5 was highly expressed, participated in G1-S transition, and was also associated with the inhibition of apoptosis." (PMID 30533424, 2018). "RBBP5 was an independent prognostic indicator of survival of HCC patients, which was in agreement with previous study that glioma patients with high RBBP5 expression had worse prognosis." (PMID 30533424, 2018).
Kabuki syndrome (2 papers, 2015 to 2023). Kabuki syndrome (KS) is a multiple congenital anomaly syndrome characterized by typical facial features, skeletal anomalies, mild to moderate intellectual disability and postnatal growth deficiency. "For example, while MLL1 does not interact with RbBP5 or Ash2L in pairwise experiments, an investigation of Kabuki syndrome missense mutations suggests that the MLL1 SET domain directly interacts with the RbBP5–Ash2L heterodimer within the context of the holocomplex." (PMID 36623730, 2023). "Analysis of Kabuki syndrome missense mutations when introduced into the MLL1 SET domain resulted in the identification of a surface, called the Kabuki interaction surface, that is required for interaction of MLL1 with the RbBP5/Ash2L heterodimer within the MLL1 core complex." (PMID 26324722, 2015).
melanoma (2 papers, 2023 to 2024). A malignant, usually aggressive tumor composed of atypical, neoplastic melanocytes. "The results showed that overexpression of RBBP5 caused the percentage of cells in the S phase to decrease and the percentage of cells in the G0/G1 phase to increase in A375 melanoma cells compared with control cells." (PMID 36866240, 2023). "Our study showed that RBBP5 was significantly downregulated in melanoma tissue and cells compared with nevi tissues and normal epithelia cells (P < 0.05)." (PMID 36866240, 2023). "Together, our study showed that the expression of RBBP5 was significantly downregulated in melanoma tissue and cells." (PMID 36866240, 2023). "In our study, we observed that partial-EMT-related markers N-cadherin and MMP-7 were upregulated, and E-cadherin was downregulated after RBBP5 knockdown in melanoma cells, which agree with previous research about cadherin switch." (PMID 36866240, 2023). "To investigate the impact of RBBP5 on the tumorigenic capacity of melanoma cells in vivo, we subcutaneously injected RBBP5-overexpressing and RBBP5-silenced A375 cells into female nude mice." (PMID 36866240, 2023). "Altogether, our study demonstrated the potential ability of RBBP5 to act as a tumor suppressor to inhibit the progression of melanoma by inhibiting the Wnt/β-catenin signalling pathways and EMT." (PMID 36866240, 2023). "Reducing RBBP5 in human melanoma cells leads to H3K4me3 downregulation and promotes cell proliferation, migration, and invasion." (PMID 36866240, 2023). "In the present study, we found that RBBP5 was a tumor suppressor factor in human melanoma,which was downregulated in melanoma tissues and cells." (PMID 36866240, 2023). "First, WB results showed that the expression of RBBP5 was significantly decreased in melanoma tissue compared with nevi and adjacent tissue (p < 0.05)." (PMID 36866240, 2023). "Our study conclusion agreed with previous studies showing that overexpression of RBBP5 can enhance the level of H3K4me3 and inhibit the progression of melanoma in vivo and in vitro." (PMID 36866240, 2023). "To further explore the correlation between WSB2 and RBBP5, we performed immunohistochemical staining on 104 melanoma paraffin sections." (PMID 36866240, 2023). "We revealed that knockdown of RBBP5 in melanoma cells promoted proliferation, clone formation, invasion, and migration." (PMID 36866240, 2023). "To explore the molecular mechanism of RBBP5 in melanoma cells, we analyzed the expression of β-catenin and c-myc, two marked target genes of the Wnt/β-catenin signalling pathway, in A375 and A2058 cells." (PMID 36866240, 2023). "Our findings verified the significance of RBBP5-mediated H3K4 modification in melanoma and the potential regulatory mechanisms of melanoma proliferation and growth, suggesting that RBBP5 is a potential therapeutic target for the treatment of melanoma." (PMID 36866240, 2023). "RBBP5 expression in melanoma and nevi specimens was detected by immunohistochemistry." (PMID 36866240, 2023). "Our study suggested that RBBP5 plays an important role in tumor progression in melanoma and might be a potential therapeutic target for the treatment of melanoma." (PMID 36866240, 2023). "Taken together, our study indicated that RBBP5 could inhibit the progression of melanoma cells in vitro and inhibit the G1/S transition." (PMID 36866240, 2023). "Functional studies showed that overexpression of RBBP5 could enhance the expression of H3K4me3 and inhibit the proliferation, migration and invasion of melanoma cells." (PMID 36866240, 2023). "Our findings reveal a novel link between RBBP5, H3K4me3, and p16 and melanoma progression." (PMID 36866240, 2023). "We explored the signalling pathway related to RBBP5 and found that RBBP5 could affect the progression of melanoma through multiple signalling pathways, including Wnt/β-catenin and epithelial-mesenchymal transition (EMT)." (PMID 36866240, 2023).
melanoma (continued). "Thus, our findings suggest that RBBP5 might be a potential therapeutic target to reverse melanoma progression." (PMID 36866240, 2023). "Thus, our study clearly proved that RBBP5 is a tumor progression inhibitor in melanoma." (PMID 36866240, 2023). "Furthermore, our research provided strong evidence that RBBP5 can increase the expression of H3K4me3, which could promote the transcription of p16 by directly binding to the promoter of p16 and inhibiting the progression of melanoma." (PMID 36866240, 2023). "However, the roles of H3K4me3 and RBBP5 in melanoma remain unknown." (PMID 36866240, 2023). "The present study sought to explore RBBP5-mediated H3K4 histone modification and the potential mechanisms in melanoma." (PMID 36866240, 2023). "Mechanistically, our data revealed that RBBP5 inactivated the Wnt/β-catenin and epithelial-mesenchymal transition (EMT) pathways (P < 0.05), leading to melanoma suppression." (PMID 36866240, 2023). "Together, our research suggested that RBBP5 could suppress the tumor growth and EMT of melanoma cells in vivo." (PMID 36866240, 2023). "However, as a part of H3K4 methyltransferase that participates in H3K4 methylation and transcriptional regulation, retinoblastoma-binding protein 5 (RBBP5) has not been well studied in melanoma." (PMID 36866240, 2023).
colon cancer (1 paper, 2018). "WDR5, RBBP5, and DPY30 are increased in tumors relative to normal tissue; however, WDR5 is expressed at the highest level and shows the most dramatic increase in expression between normal tissue and colon tumor tissue so it was selected for further study." (PMID 29925347, 2018). "The contribution of WDR5 to DNA fidelity may or may not be independent of its role in the WRAD subcomplex as RBBP5 did not affect viability in a panel of colon cancer cells." (PMID 29925347, 2018).
esophageal carcinoma (1 paper, 2021). A primary or metastatic malignant neoplasm involving the esophagus. "Expression of the WRAD subunits ASH2L and RbBP5 was positively correlated with NORAD expression in esophageal carcinoma tissues." (PMID 34587992, 2021).
gastric cancer (1 paper, 2015). A primary or metastatic malignant neoplasm involving the stomach. "In the present study, we showed that components of WRAD (WDR5, RBBP5 and ASH2L) can inhibit proliferation of gastric cancer cells, suggesting that DPY30 act through the increased H3K4MT activity." (PMID 26147337, 2015).
Intellectual disability (1 paper, 2014). "RBBP5 co-purifies with the noncoding RNA 116HG, paternal deletion of which leads to Prader-Willi syndrome, a disease characterized in part by intellectual disability." (PMID 25187168, 2014).
leukemia (1 paper, 2024). A malignant (clonal) hematologic disorder, involving hematopoietic stem cells and characterized by the presence of primitive or atypical myeloid or lymphoid cells in the bone marrow and the blood. "Specifically, WDR5 and RBBP5 of the mixed-lineage leukemia histone methylation complex catalyze histone H3 methylation on lysine K4 (H3K4) that occupies transcription start sites and hydroxyurea (HU)-stalled replication forks." (PMID 37940188, 2024).
microcephaly (1 paper, 2025). A congenital or acquired developmental disorder in which the circumference of the head is smaller than normal for the person's age and sex. "It is also interesting to note that loss-of-function mutations in RBBP-5 in humans have recently been identified and associated with neurodevelopmental disorder, short stature and microcephaly, highlighting the importance of H3K4 methylation for neuronal function." (PMID 40799728, 2025).
nasopharyngeal carcinoma (1 paper, 2024). A carcinoma arising from the nasopharyngeal epithelium. "LINC00930 was first reported in nasopharyngeal carcinoma, where it binds the RBBP5 and GCN5 complexes to the PFKFB3 promoter, elevates H3K4 trimethylation and H3K9 acetylation levels, transactivating PFKFB3, thereby promoting glycolytic flux and cell cycle progression." (PMID 38789960, 2024).
cancer (15 papers, 2015 to 2025). A tumor composed of atypical neoplastic, often pleomorphic cells that invade other tissues. "For example, DPY30 was significantly positively correlated with SETD1A, SETDB1 and RBBP5, which have been reported to promote the occurrence and progression of cancers." (PMID 34090418, 2021). "Although the core subunits of KMT2 complexes such as WDR5, RBBP5, DPY30, and ASH2L are rarely deleted or carry genetic mutations, they are frequently amplified or upregulated in human cancers and act as oncogenes." (PMID 33302406, 2020). "Overexpression of RBBP5 promotes cell cycle progression and proliferation and induces chemotherapy resistance of cancer cells." (PMID 30533424, 2018). "TLR4 activation inhibits cancer stem cell properties by reducing retinoblastoma binding protein 5 (RBBP5)." (PMID 30279357, 2018). "A comparable AlphaScreen signal was observed for MLL1 wild‐type and all cancer variants, which is indicative of a similar interaction of all MLL1 proteins with the RBBP5/ASH2L heterodimer." (PMID 28182322, 2017). "Similar to WDR5, the expression of RBBP5 is also increased in many cancers." (PMID 33302406, 2020). "In addition to degrading total and chromatin-bound WDR5, MS67 also decreased chromatin-bound fractions of MLL complex components, such as MLL, RBBP5, and Menin, and c-MYC, another WDR5 partner in cancer." (PMID 34586829, 2021).
tumor (7 papers, 2018 to 2023). "The percentage of positive RBBP5 staining was 12.3% (13/106) in tumor tissues, 24% (24/100) in adjacent tissues, and 21.8% (5/23) in nevi tissues." (PMID 36866240, 2023). "We also confirmed endogenous interaction between FOXQ1 and RbBP5 in various tumor types, including TNBC." (PMID 36319643, 2022). "In conclusion, our study provided the first evidence that RBBP5 was conspicuously overexpressed in HCC and was associated with Ki-67 expression, AFP, TNM stage, tumor size, and poor prognosis." (PMID 30533424, 2018). "High RBBP5 expression was significantly associated with elevated level of AFP, advanced TNM stage, high Ki-67 expression, larger tumor size, and poor prognosis." (PMID 30533424, 2018). "Retinoblastoma binding protein 5 (RBBP5) was determined as the binding protein of RB transcriptional corepressor 1 (RB1) which is one of the best studied tumor suppressor proteins." (PMID 30533424, 2018). "RBBP5, also defined as a binding protein of retinoblastoma, is one of the best studied tumor suppressors." (PMID 30533424, 2018). "Amplification and overexpression of the RBBP5 gene were found in patient-derived tumor samples." (PMID 37974198, 2023). "We obtained the opposite results in the RBBP5-overexpressing group of xenogeneic tumor tissues." (PMID 36866240, 2023). "Furthermore, the expression ofβ-catenin and c-myc in the Wnt/β-catenin signalling pathway was increased in the RBBP5 knockdown group in xenogeneic tumor tissues of nude mice, and N-cadherin and MMP-7 in EMT also increased." (PMID 36866240, 2023). "RBBP5 regulates DNA-damaging agent-induced apoptosis in tumor cells." (PMID 30533424, 2018). "Furthermore, RBBP5 is a core member of MLL/SET (mixed lineage leukemia/set-domain containing) complexes involved in tumor cell cycle progression through an MLL–E2F axis which controls the expression of cyclins E, A, and B." (PMID 30533424, 2018). "Our data has repeatedly identified FOXQ1 bound to intact MLL core complex as shown through FOXQ1 TAP-MS in HEK293 cells and FOXQ1 or RbBP5 IP from the mammary cell model (HMLE/FOXQ1), TNBC cell lines, and tumor samples." (PMID 36319643, 2022). "Direct interaction of FOXQ1 and RbBP5 was further validated in TNBC cell lines and various human tumor samples, including TNBC." (PMID 36319643, 2022). "High RBBP5 expression was significantly correlated with high serum level of AFP (P = 0.019), advanced TNM stage (P = 0.019), larger tumor size (P = 0.012), and high Ki-67 expression (P < 0.001)." (PMID 30533424, 2018). "Moreover, Nutlin also regulated the tumor-promoting HSF1 targets CDC6, ITGB3BP, RBBP5, BST2, and FBLN1." (PMID 34188043, 2021). "Cluster 1 was characterized by upregulation of tumor-suppressing genes: HNF1B, CCNDBP1, PATJ, EPB41L3, MARVELD2, PTEN in conjunction with cell-cycle genes – GSPT1, GPR19, EAPP, KIT, CDKL1, and stem cell markers – RBBP5, NANOG, NCSTN, ERG, including quiescent stem cell markers—FOXP1, SMARCA2." (PMID 36348001, 2022).
RBBP5 also shares sentences with these, for which no sentence is quoted: multiple myeloma (2 papers); bladder cancer (1); Cirrhosis (1); colitis (1); colon adenocarcinoma (1); Infertility (1); lung squamous cell cancer (1); metastatic tumor (1); migraine (1); neurodevelopmental disorder (1); ovary cancer (1); Prader-Willi syndrome (1); skin cancer (1).